HTR2A (5-hydroxytryptamine receptor 2A)
Diseases named in the same sentence as HTR2A in open-access papers (continued):
Sharing a sentence is not in itself a finding about the gene and the disease.
depression (109 papers, 2011 to 2025). "HTR2A encodes a serotonin receptor expressed in RG, and mutations in this gene are associated with neuropsychiatric disorders including major depressive disorder and obsessive-compulsive disorder." (PMID 40593693, 2025). "Further genetic variants related to serotonergic function, such as HTR2A (serotonin receptor 2A), have shown associations with stress sensitivity and depression, with evidence for both genetic and epigenetic contributions." (PMID 41300812, 2025). "HTR2A encodes one of the receptors for serotonin, a neurotransmitter with many roles, which play an important role in major depressive disorder." (PMID 36072347, 2022). "Expression levels of HTR2A mRNA were increased in peripheral blood mononuclear cells of MDD, and mRNA levels of HTR2A itself were associated with depression severity." (PMID 33519430, 2020). "Finally, a predicted binding site for miR-1304 contains a polymorphism (rs3125) in the HTR2A serotonin receptor gene, previously associated with endophenotypes for depression." (PMID 38872198, 2024). "One study reported that 5-hydroxytryptamine receptor 2A functional rs6311 polymorphism may modulate the severity of depression symptoms in children with autism spectrum disorder." (PMID 31281445, 2019). "The gene encoding 5-HT2A (HTR2A) is considered to be a candidate gene for depression." (PMID 22619623, 2012). "In addition, the HTR2A gene has been directly associated with major depressive disorder." (PMID 24959950, 2014). "The relationship between genetic variants and depression severity or remission was also evidenced by findings involving SLC6A4, ABCB1, and HTR2A." (PMID 40725795, 2025). "The results of this study targeting the HTR2A gene provide a foundation for the development of innovative therapeutic strategies for a broad range of neurological disorders, including anxiety, depression, attentional deficits, and cognitive dysfunction." (PMID 37346271, 2023). "These genes are involved in the complex pathological mechanism of depression, including the neurotransmitter system (e.g., HTR2A and SLC6A4), neurotrophin (e.g., BDNF), hypothalamic-pituitary-adrenal (HPA) axis (e.g., CRH), and inflammation (e.g., IL6, TNF)." (PMID 36072347, 2022). "This study aims to estimate the contribution of 11 polymorphisms in the genes SLC6A4 (5HTT), HTR1A, HTR2A, HTR1B, SLC6A3 (DAT1), DRD4, DRD2, COMT, and BDNF to suicidal behavior and severity of symptoms of depression and anxiety in the Russian population." (PMID 34199792, 2021). "Cyclobenzaprine, as well as another drug named the anti-depression drug amitriptyline in this cluster, exhibits antagonistic effects on the 5-hydroxytryptamine receptor 2A and possesses a tricyclic structure." (PMID 33075523, 2020). "Preclinical studies in humans provided support for the involvement of HTR2A in major depressive disorder (Fabbri, Marsano, & Serretti, 2013)." (PMID 32304290, 2020). "HTR2A is a protein which functions as a receptor for various drugs and psychoactive substances, Nefazodone acts on HTR2A and has palliative effect on depression." (PMID 33106157, 2020). "Additionally, we detected 4 P-SMRs involved in Alzheimer’s disease (Psen2), Parkinson’s disease (Dnajc6) and major depression disorder (Htr2a and Htr5a)." (PMID 32992647, 2020). "In addition, CHSGS and fluoxetine have similar effects in improving blood rheology, and both can alleviate the hypercoagulable state of blood via the platelet 5-hydroxytryptamine receptor 2A (5-HT2A) pathway in rats of depression." (PMID 39295891, 2020). "Potentials of targeting HTR2A genetics in depression prevention deserve further studies." (PMID 31258491, 2019). "Indeed, this research proposed HTR2A gene as a potential biomarker for clinical improvement of depression." (PMID 24959950, 2014).
depression (continued). "Additionally, there is an association between depression and the SNP rs6296 of HTR1B, HTR2A rs6561333 with cocaine dependence, HTR3B rs11606194 over time to relapse after smoking cessation and with nicotine dependence, and HTR3B rs1176744 with alcohol and nicotine dependence." (PMID 39731452, 2025). "Studies have investigated the association between anxiety and depression with polymorphisms in candidate genes involved in the neurotransmitter system and the stress response, such as Catechol-O-methyltransferase (COMT), Serotonin receptor 2A (HTR2A) and FK506-binding protein 51 (FKBP5)." (PMID 36834016, 2023). "In the field of depression, 5-HT-related genes (e.g., HTR1A, HTR2A, and SLC6A4) and their SNPs are also the predominantly researched pharmacodynamic genes." (PMID 37581520, 2024). "These few studies, implicating the roles of synaptic plasticity candidate genes BDNF and CREB1, as well as serotonin receptor gene HTR2A and folate pathway gene MTHFD1L, have exclusively focused on depression as a relevant disorder, or on depressive symptoms." (PMID 34577549, 2021). "In this study, we estimated the contribution of SLC6A4 (5HTT), HTR1A, HTR2A, HTR1B, SLC6A3 (DAT1), DRD4, DRD2, COMT, and BDNF genes to the suicidal behavior and severity of symptoms of depression and anxiety in the East-Slavic population of Russia." (PMID 34199792, 2021). "Our results showed that 5-hydroxytryptamine receptor 2A (HTR2A), a member of the serotonin receptor family, was significantly upregulated in the PFC of mice with depression-like phenotype, which is consistent with clinical studies of MDD patients." (PMID 34744165, 2021). "A number of DEGs detected in this study have also been associated with altered neuronal function, including reduced HTR2A and increased HTR2C expression in individuals suffering from depression and Huntington’s disease." (PMID 27809765, 2016). "Focusing on the serotonergic system—the foundation of the monoamine hypothesis of depression—we observed a significant reduction in 5-HT levels in the PFC following FMT, along with H3K27me3-mediated transcriptional repression of key genes including Tph2, Htr1d, Htr2a, Htr3a, Htr6, and Htr7." (PMID 41041075, 2025). "Since it has been proposed that low-grade inflammation promotes both obesity and depression, it might be hypothesised that methylation of HTR2A could interact with obesity and depressive disorders by hindering the binding of HIF, HESF and CREB to the HTR2A gene promoter region." (PMID 24959950, 2014).
Anxiety (62 papers, 2008 to 2026). Intense feelings of nervousness, tension, or panic often arise in response to interpersonal stresses. "In the present study, we demonstrate that short-hairpin RNAs (shRNA) targeting knockdown of the human HTR2A gene can modify neuronal circuits underlying both anxiety and memory." (PMID 38509093, 2024). "Among those, we observed genes that have been associated with PTSD in previous human studies (e.g., DRD2 and HTR2a) or linked to anxiety or PTSD-like behaviors in humans or animal models (Igf2, Grm2, Clock, Trhr)." (PMID 30705647, 2018). "In rodents, the excitatory effects of cortical Htr2A are thought to promote anxiety and impulsivity." (PMID 21829518, 2011). "In rodents, genetic deletion of cortical Htr2A diminished anxiety levels, and pharmacological modulation of Htr2A within the prefrontal cortex has bidirectional effects on impulsivity with stimulation increasing and antagonism decreasing impulsivity." (PMID 21829518, 2011). "The genes CCK, POMC, MCHR1, GABRA6, HTR2A and DRD2, which associated with heat score in at least one brain area, are known to modulate emotional states like anxiety and satiety or even sexual motivation." (PMID 21504592, 2011). "Similarly, neonatal rat exposure to predator odor stress was associated with altered 6mA levels in the amygdala, and sex-specific differences in 5-Hydroxytryptamine Receptor 2A (Htr2A) promoter repression and anxiety-like behavior." (PMID 38726308, 2024). "In the present study, we designed a shRNA to knockdown the HTR2A gene and demonstrate a decrease in spontaneous electrical activity in human iPSC-differentiated neurons in vitro as well as enhanced memory and a reduction in anxiety in mice and rats in vivo." (PMID 38509093, 2024). "Moreover, genetic manipulation of lysine methyltransferases in mice was shown to alter Htr2a expression and histone methylation has thus been proposed as an epigenetic drug target for anxiety and depression." (PMID 37684227, 2023). "Moreover, alterations of anxiety-like behaviors were observed in 5-HT1A or 5-HT2A knock-out mouse lines (Htr1a or Htr2a)." (PMID 32594910, 2020). "Currently, though the alteration of GABAA and 5-HT receptors under strong oxidative stimulation is unclear, our result in some extent suggested that overexpression of GABRA1, GABRA2, HTR1A, HTR1B, and HTR2A may be involved in oxidative stress-induced anxiety." (PMID 33178009, 2020). "HTR1A, HTR1B, HTR2A, and HTR2B were commonly targeted in preclinical studies for the anxiety treatment as well as the anxiolytic-like studies of SZJ." (PMID 33178009, 2020).
psychosis (39 papers, 2009 to 2025). "Increased DNA methylation at rs6313 in peripheral leukocytes was reported in major psychosis patients with suicidal tendency, suggesting the potential involvement of HTR2A promoter hypermethylation in psychosis." (PMID 28054990, 2017). "Five genes, DRD2, DRD3, HTR2A, OPRD1 and HTR7, are found shared by psychosis network and antipsychotics network." (PMID 32273551, 2020). "Firstly, we have used WT or Htr2a-/- mice, which by themselves are clearly not a model for psychosis." (PMID 30713996, 2018).
Parkinson disease (22 papers, 2009 to 2025). A progressive degenerative disorder of the central nervous system characterized by loss of dopamine producing neurons in the substantia nigra and the presence of Lewy bodies in the substantia nigra and locus coeruleus. "Genetic variant of HTR2A associates with risk of impulse control and repetitive behaviors in Parkinson’s disease." (PMID 40264664, 2025). "Although loss of Omi/Htr2A is neuroprotective, and Omi/Htr2A has been linked to Parkinson’s suggesting important roles in controlling neuron apoptosis, it is not clear whether non-apoptotic caspase activity involves the release of Omi/Htr2A (or Smac/Diablo)." (PMID 35281082, 2022).
Obesity (16 papers, 2009 to 2025). Accumulation of substantial excess body fat. "In humans, genetic studies have reported that polymorphisms in Htr genes (for example, HTR1A, HTR1Dβ, and HTR2A) are associated with obesity." (PMID 33692832, 2021). "It has been identified as a genetic variant, namely, rs17069005 in HTR2A gene associated with obesity at last follow-up, but the role of HTR2A in mediating the effects on cattle adipocyte differentiation remains unexplored." (PMID 29899319, 2018). "Among them the serotonin 2A receptor, which is encoded by the 5-hydroxytryptamine receptor 2A (HTR2A) gene, has been involved in the pathogenesis of major psychiatric disorders and obesity." (PMID 24959950, 2014). "Previous studies have shown that HTR2A agonist could increase lipid accumulation and 5-HT suppress lipolysis in 3T3-L1 adipocytes and a genetic variant in HTR2A associated with obesity." (PMID 29899319, 2018). "However, although polymorphisms of the HTR2A gene have been associated with both obesity and psychiatric disorders, the role of HTR2A gene methylation in these illnesses remains uncertain." (PMID 24959950, 2014). "In addition, the 5-hydroxytryptamine receptor 2A gene (HTR2A), which encodes a serotonin receptor subtypes, has been identified in the placental trophoblast and fetal capillary endometrium and contributes to the pathogenesis of obesity and psychopathological conditions." (PMID 36431006, 2022). "Increased expression of hepatic htr2a in diet-induced obesity can therefore contribute to hepatosteatosis." (PMID 32978487, 2020). "On the other hand, increased expression of hepatic serotonin receptor 2a (htr2a) in diet-induced obesity contributes to hepatosteatosis." (PMID 32978487, 2020). "Genes previously-reported to be associated with obesity and that reside within marker intervals at our peak LOD scores include GHRL, PPARG, HTR2A and ESR2." (PMID 21062459, 2010). "Of particular interest, in the stress-induced obesity, HTR2A interacts with CCK and GHSR." (PMID 39062927, 2024). "Htr2a was upregulated in the ARC of diet-induced obese rats, whereas in humans, 5-HT2AR correlated positively with BMI and a polymorphism in the gene encoding 5-HT2AR has been associated with obesity." (PMID 26769798, 2016).
insomnia (14 papers, 2015 to 2025). A sleep disorder characterized by difficulty in falling asleep and/or remaining asleep. "We could predict the role of VVO in modulating the serotonergic synaptic pathway in the treatment of insomnia, and this modulation was associated with MAOB, MAOA, PTGS2, HTR2A, and SLC6A4." (PMID 40004189, 2025). "In addition, 5-HT1A (HTR1A) and 5-HT2A (HTR2A) have been identified as common targets for the treatment of insomnia, in both clinical and basic studies, as well as prevenient studies of ZSS for the treatment of insomnia." (PMID 35002696, 2021). "The results from the PPI analysis show that the targets of VVO for the treatment of insomnia mainly involve MAOB, DRD2, MAOA, IL1B, PTGS2, HTR2A, SLC6A4, and ESR1." (PMID 40004189, 2025). "In summary, our research findings have elucidated that VVO treats insomnia through a variety of components and multiple targets, with MAOB, MAOA, SLC6A4, HTR2A, and others at serotonergic synapses playing a vital role in the process of VVO treating insomnia." (PMID 40004189, 2025).
migraine (14 papers, 2015 to 2025). "Briefly, 5-HT and its receptors, such as HTR2A, HTR2C are implicated in migraines." (PMID 36079577, 2022).
mood disorder (13 papers, 2012 to 2025). A cognitive disorder a disturbance in which the person's mood is hypothesized to be the main underlying feature. "We seized on the genes HCRT, KALRN, and HTR2A to substantiate the connection to mood disorders." (PMID 34987393, 2021). "Serotonin is responsible for regulating a wide variety of mood disorders, mostly through the action of serotonin receptors (HTR1A and HTR2A) and serotonin transporter (SERT)." (PMID 39202385, 2024).
Hepatic steatosis (12 papers, 2018 to 2025). Steatosis is a term used to denote lipid accumulation within hepatocytes. "Here, we show that Htr2a (a gene involved in hepatic steatosis) and Htr2b (a gene activated in PH models) are needed for liver regeneration." (PMID 35765850, 2022). "As gut-specific tryptophan hydroxylase 1 (Tph1) knockout mice and liver-specific Htr2a knockout mice are resistant to high-fat diet (HFD)-induced hepatic steatosis, the gut TPH1-liver-HTR2A axis is a promising drug target for NAFLD." (PMID 35765850, 2022). "Recently, it was shown that the inhibition of HTR2A signaling in vivo by blocking 5-HT synthesis ameliorates hepatic steatosis." (PMID 33081272, 2020). "We also examined GDS in terms of the regulation of hepatic steatosis and inflammation through the HTR2A/PPARγ pathway." (PMID 32477107, 2020). "Specifically, HTR2A knockdown and evaluation of PPARγ agonist activity revealed that HTR2A promoted hepatic steatosis and inflammation by activating PPARγ2." (PMID 32477107, 2020). "Here we demonstrate that inhibition of gut-derived serotonin synthesis ameliorates hepatic steatosis through a reduction in liver serotonin receptor 2A (HTR2A) signaling." (PMID 30446669, 2018). "From these results, we confirmed that the protective effect against hepatic steatosis by reducing GDS production was highly specific for hepatic HTR2A." (PMID 30446669, 2018). "Indeed, liver-specific Htr2a knockout mice are resistant to high-fat diet induced hepatic steatosis and increased fat in the liver." (PMID 36313344, 2022). "Furthermore, compared to HFD-fed WT mice, HFD-fed MC4RKO mice showed more severe hepatic steatosis and TG content increase and milder recovery of these parameters after peripheral neural blockade and treatment with the HTR2A antagonist." (PMID 35765850, 2022). "Furthermore, the inhibition of hepatic serotonin receptor 2A (HTR2A) signaling in vivo by blocking the synthesis of 5-HT improves liver steatosis, as well as hyperglycemia and dyslipidemia." (PMID 33081272, 2020). "Furthermore, HFD-fed Htr2a LKO mice showed decreased hepatic steatosis as examined by histology, NAS, and hepatic TG concentrations without affecting BW, glucose tolerance, insulin sensitivity, and plasma lipid profiles." (PMID 30446669, 2018). "Thus, SLZBS may mitigate hepatic steatosis by inhibiting the expressions of HTR2A in the liver and TPH-1 in the small intestine as well as by reducing the levels of 5-HT in the liver and small intestine." (PMID 38720776, 2024). "Some emerging evidence suggests that serotonin production, which can act via the 2A serotonin receptor (HTR2A) to upregulate the expression of lipogenic proteins and increase hepatic steatosis, in the periphery may be instrumental to the pathophysiology of NAFLD." (PMID 36899407, 2023). "Htr2a in the liver may therefore contribute to hepatic steatosis in mice fed a high-fat diet." (PMID 33364514, 2020). "Moreover, selective HTR2A antagonist treatment prevents HFD-induced hepatic steatosis." (PMID 30446669, 2018). "Importantly, these results are supported by the expression of tissue-specific HTRs, such as HTR1B, HTR2A, HTR2B and HTR7, in the liver, the relationship of HTR2A with hepatic steatosis and that of HTR2B with hepatocyte proliferation." (PMID 35765850, 2022). "Taken together with data from Tph1 GKO and Htr2a LKO mice, we have identified a previously unknown enterohepatic signaling pathway for hepatic steatosis mediated by GDS and hepatic HTR2A." (PMID 30446669, 2018). "Here we demonstrate that inhibition of GDS synthesis by Tph1 GKO mice ameliorates hepatic steatosis independent of systemic energy homeostasis and Htr2a LKO mice revealed a phenocopy of Tph1 GKO mice." (PMID 30446669, 2018). "Both gut-specific Tph1 knockout mice and liver-specific Htr2a knockout mice are resistant to HFD-induced hepatic steatosis, without affecting systemic energy homeostasis." (PMID 30446669, 2018).
Hepatic steatosis (continued). "Both Tph1 GKO and Htr2a LKO mice were effective only in HFD-induced liver steatosis without altering systemic energy homeostasis which suggest that blocking enterohepatic signaling pathways mediated by GDS and HTR2A represses TG accumulation in the liver." (PMID 30446669, 2018). "Inactivation of HTR2A signaling in the liver using Htr2a LKO attenuated hepatic steatosis independent of systemic energy homeostasis." (PMID 30446669, 2018). "Moreover, a selective HTR2A antagonist showed efficacy in improving hepatic steatosis as predicted by Tph1 GKO mice and Htr2a LKO mice phenotypes in HFD-induced hepatic steatosis." (PMID 30446669, 2018). "As 5-HT produced in the SI is transported via portal circulation to the liver for subsequent binding with HTR2A, we examined the kinetics of serum 5-HT levels in HFD-fed WT and HFD-fed MC4RKO mice, and in patients with fatty liver disease, to determine whether 5-HT levels reflect hepatic steatosis." (PMID 35765850, 2022). "GDS directly promoted the development and progression of NASH by hepatic HTR2A, rather than HTR2B or HTR2C, those similar to hepatic steatosis was ameliorated with liver-specific Htr2a knockout and the deletion of GDS." (PMID 32477107, 2020).
Hypertension (11 papers, 2008 to 2025). The presence of chronic increased pressure in the systemic arterial system. "A more recent study also reported associations between several HTR2A single nucleotide polymorphisms (SNPs), including rs6313/T102C, and hypertension risk, though the direction and magnitude of effect varied between cohorts." (PMID 41468376, 2025). "Additional evidence suggests that HTR2A plays a role in cardiac remodelling associated with hypertension." (PMID 41468376, 2025).